SIRT1 (sirtuin 1)
Diseases named in the same sentence as SIRT1 in open-access papers (continued):
Sharing a sentence is not in itself a finding about the gene and the disease.
cardiovascular diseases (202 papers, 2009 to 2025). "SIRT1 modulates several cellular pathways to regulate complex cellular processes associated with cardiovascular disorders." (PMID 41567643, 2025). "In cardiovascular disease, the activation and upregulation of SIRT1 provide cardiac protection against a range of pathogenic mechanisms, such as oxidative stress and inflammation." (PMID 39680523, 2024). "Conversely, ROS have been associated with decreased sirtuin 1 (SIRT1) activity in both cardiovascular diseases and kidney injuries." (PMID 39595187, 2024). "A number of previous studies have reported that polymorphisms in SIRT1 are associated with cardiovascular disease across races." (PMID 35469171, 2022). "Sirtuin-1 plays an essential role in the regulation of angiogenesis, a protective role against oxidative stress and cardiovascular disease and higher expression levels of sirtuin-1 are associated with reducing disease." (PMID 34421827, 2021). "On the other hand, SIRT1 and SIRT6 inhibitors have aggravated cardiovascular diseases, which underlines the need for a reliable SIRT1 and SIRT6 activators." (PMID 34650436, 2021). "Cardiovascular disease studies have found that inhibition or deficiency of SIRT1 in SIRT1 knockout mice increases ER stress-induced heart damage." (PMID 32312941, 2020). "Endogenous SIRT1 plays a pivotal role in mediating the cell death/survival process and has been implicated in the pathogenesis of cardiovascular diseases." (PMID 32016113, 2020). "Immense amounts of concrete research have demonstrated that endogenous SIRT1 is tightly linked to the cardioprotection of various cardiovascular diseases for its pivotal role in increasing resistance to oxidative damage." (PMID 33062139, 2020). "In contrast, SIRT1 inhibition causes OS in patients with cardiovascular disease, impaired endothelium‐dependent vasorelaxation and hypoxia‐induced angiogenesis." (PMID 32286000, 2020). "This is an initial Turkish population based study that needs to be larger sample size to better interpret the results for associations between the SIRT1 polymorphisms and the risk of cardiovascular disease." (PMID 24587358, 2014). "For example, humans who practice dietary restriction have increased levels of SIRT1, which have been strongly associated with protection against several metabolic or cardiovascular diseases." (PMID 22321768, 2012). "Similarly to the yeast Sir2, SIRT1 exerts longevity effects against aging-associated pathologies, such as neurodegeneration, metabolic dysfunction, and cardiovascular diseases." (PMID 36901738, 2023). "SIRT1 gene SNPs have been associated with SIRT1 levels in patients with cardiovascular diseases." (PMID 36747995, 2023). "Indeed, SIRT1 is differently regulated in many oxidative-stress-associated diseases i.e., neurodegenerative and cardiovascular disease and increases insulin sensitivity in T2D and aging." (PMID 31614723, 2019). "The favorable effects on lipid profile suggest that SIRT1 activation may have a beneficial role in patients at risk of developing or with established cardiovascular disease." (PMID 23770971, 2013). "Moreover, considering that SIRT1 gene polymorphisms can affect the protein expression in cardiovascular diseases, we speculated that the polymorphisms in SIRT1 gene might have an impact on the susceptibility to MI as well." (PMID 25706717, 2015). "Sirtuin 1 (SIRT1) is an NAD+-dependent deacetylase implicated in various physiological and pathological processes, including cardiovascular diseases." (PMID 41302436, 2025). "Sirtuin family proteins, particularly Sirt1, are critical regulatory factors involved in autophagy and exert protective effects in cardiovascular diseases." (PMID 40486507, 2025).
cardiovascular diseases (continued). "Studies have shown that the AMPK / SIRT1 pathway mediates the protective effects of various cardiovascular diseases." (PMID 38172692, 2024). "SIRT1, as a post‐translational regulator, plays a role in regulating various diseases including diabetes, cancer, cardiovascular diseases and neurodegenerative diseases." (PMID 39010253, 2024). "Resveratrol, a natural activator of Sirt1, has important therapeutic value in the management of the cardiovascular disease." (PMID 37487007, 2023). "miR-34a influences lipid metabolism by inhibiting the Sirtuin 1 (SIRT1) pathway as well as stimulating pro-inflammatory cytokines such as IL-1b, IL-7A CRP and TNF-α which are strongly associated with cardiovascular diseases." (PMID 36071532, 2022). "Emerging evidence indicates that the crucial role of SIRT1 has attracted extensive attention in cardiovascular disease with a critical ability of SIRT1 to resist DOX-induced oxidative damage and cell death." (PMID 36235670, 2022). "Sirtuin 1 (SIRT1) is a deacetylase that has been previously shown to have a protective effect against cardiovascular disease in the context of resisting sustained oxidative stress." (PMID 35252405, 2022). "Previous multiple studies considered SIRT1 as a pro-longevity regulator against aging-related diseases like neurodegeneration and cardiovascular disease." (PMID 36507335, 2022). "An impairment of cardiac Sirt1 signaling is reported to contribute to the pathogenesis of cardiovascular diseases." (PMID 35207470, 2022). "Sirtuin1 (Sirt1), a cellular nicotinamide adenine dinucleotide- (NAD+-) dependent deacetylase that catalyses deacetylation of proteins, is the most studied one in seven members of the sirtuin family (Sirt1-Sirt7), especially in cardiovascular diseases." (PMID 35103095, 2022). "Then, we highlight the targets (SIRT1 and mTOR) that regulating cellular senescence in cardiovascular disorders." (PMID 35111365, 2022). "As it is well-known, hyperglycemia, insulin resistance and diabetes mellitus are major determinants of cardiovascular diseases, and the glucose-lowering property of SIRT1 is thought to contribute to its protective function toward cardiovascular diseases." (PMID 34690807, 2021). "A clinical trial showed that betalains-/betacyanins-rich supplements (50 mg per day for 14 days) increased the levels of sirtuin-1 and decreased the levels of lipoxygenase-1 and C-reactive protein in patients with cardiovascular disease." (PMID 33925891, 2021). "In terms of cardiovascular disease, the elevation of SIRT1 via either a genetic approach or CR can bring about amelioration of age-dependent cardiac hypertrophy." (PMID 34768917, 2021). "Accumulating evidence has shown that Sirt1 plays a crucial role in cardiac protection in various cardiovascular diseases through a complex signaling network, including autophagy and apoptosis." (PMID 34356358, 2021). "As a ubiquitous molecule with a role in multiple cell functions, the relationship between SIRT1 and cardiovascular disease is not limited to endothelial function." (PMID 34690807, 2021). "SIRT1 is reported to be a novel therapeutic target for cardiovascular disease with effective deacetylase activity controlling multiple cellular processes." (PMID 34216536, 2021). "SIRT1 is the first member of sirtuins family and has been extensively investigated because of its critical protective effects against cardiovascular diseases." (PMID 34336116, 2021). "The purpose of this study was to explore the effect of miR-34c on PDGF-BB-induced HAVSMCs phenotypic transformation and proliferation via PDGFR-β/SIRT1 pathway, so as to find a new method for early diagnosis and treatment of cardiovascular disease." (PMID 34110576, 2021). "The results of our study, showing that mangiferin alleviates MI insult largely by up‐regulating cardiomyocyte Sirt1, contribute to the body of research showing that Sirt1 activation is beneficial in cardiovascular diseases." (PMID 33523605, 2021).
cardiovascular diseases (continued). "Although a number of targets of oxidative-stress-responsive miRNAs have been identified, e.g., Nrf2, SIRT1, and NF-κB, future studies are still needed to determine further potential targets and their links to cardiovascular disease." (PMID 31948131, 2020). "Resveratrol, a phenolic compound and a sirtuin 1 pathway activator, has known dietary benefits and is used as a treatment for anti-inflammatory and cardiovascular diseases." (PMID 32089765, 2020). "The histone deacetylase sirtuin-1 is a key enzyme in cellular processes such as senescence of tissues, cell survival, antioxidative properties, cardiovascular disease and muscle wasting conditions." (PMID 32024036, 2020). "SIRT1 is the first member to be found in this sirtuin family and is also widely studied for its prominent protective effectiveness on cardiovascular diseases." (PMID 31210844, 2019). "Hereby, the increase in SIRT1 levels was explained as a compensatory mechanism to induce the production of antioxidants against oxidative stress in patients with cardiovascular disease." (PMID 31143479, 2019). "Sirt1 is found as an inflammation regulator in cardiovascular diseases and participates in immune responses." (PMID 31847890, 2019). "Sirt1 plays a central role in regulating a variety of cellular processes related to heart development and cardiovascular diseases." (PMID 31847890, 2019). "Resveratrol is a Sirt-1-specific activator, which also exerts cardioprotective effects that regulate redox signalling during oxidative stress and autophagy during cardiovascular disease (CVD)." (PMID 27211317, 2016). "In one of our studies, in the patients with cardiovascular diseases (mean age: 58.99 ± 10.56), we found a positive relation with SIRT1 protein and age whose role in aging is also gaining importance by other researches." (PMID 25785999, 2015). "Secondly, a decrease in SIRT1 expression levels with age can significantly impair vascular function; for instance, heightened endothelial dysfunction can contribute to the progression of cardiovascular diseases." (PMID 40563894, 2025). "Increasing evidence highlights that some natural activators of SIRT1 may be interesting in mitigating the development of cardiovascular diseases." (PMID 41228388, 2025). "The concept of using nutraceuticals-based interventions targeting SIRT1 may pave the way for innovative strategies in cardiovascular diseases." (PMID 41228388, 2025). "SIRT1 increase the expression of endothelial nitric oxide synthase, leading to enhanced nitric oxide production, thus preventing telomere shortening and protecting against vascular aging and cardiovascular diseases." (PMID 39597901, 2024). "SIRT1 has been widely recognized to be involved in the regulation of cellular metabolism, oxidative stress, inflammation, and apoptosis, all of which contribute to the development of cardiovascular diseases." (PMID 39010253, 2024). "SIRT1 plays an important role in the regulation of aging and age‐related cardiovascular diseases." (PMID 37823125, 2023). "SIRT1 positively regulates autophagy in cardiovascular diseases." (PMID 37754811, 2023). "Sirt1 stimulates nitric oxide synthase (eNOS) gene transcription and mRNA stability, thereby resulting in endothelial relaxation, a mechanism that is always compromised to some degree in patients with different cardiovascular diseases." (PMID 37324476, 2023). "SIRT1 plays a key role in the pathogenesis of cardiovascular diseases." (PMID 36843938, 2023). "Sirt1 acts as a protector when suffering from cardiovascular disease and other disorders." (PMID 35103095, 2022). "Therefore, this enzyme has become a feasible target to treat cardiovascular diseases, and many SIRT1 activators, of a natural or synthetic origin, have been identified." (PMID 36235072, 2022). "SIRT1 activation protects various types of cardiovascular diseases." (PMID 36359987, 2022). "SIRT1 is considered a promising new target for treating cardiovascular disease." (PMID 36188570, 2022).
cardiovascular diseases (continued). "It has been reported that resveratrol could inhibit the oxidative stress-induced proliferation of VSMCs by activating SIRT1 signaling pathway, thereby improving cardiovascular diseases." (PMID 35722093, 2022). "Moreover, we highlight the role of SIRT1 and mTOR in regulating senescence during age-related cardiovascular diseases." (PMID 35111365, 2022). "Sirtuin-1 affects atherosclerosis and probably can prolong the lifespan of human cell so it has been suggested that activation of this protein may prevent cardiovascular diseases." (PMID 33925891, 2021). "As the SIRT1 inhibitor worsens cardiovascular diseases, a reliable SIRT1 activator may be needed for the therapeutic benefit." (PMID 34650436, 2021). "Moreover, SIRT1 can play a protective role in various cardiovascular diseases through diverse cellular functions." (PMID 33859776, 2021). "Substantial R&D has been invested in the quest of compounds that could boost SirT1 activity for the treatment of cardiovascular diseases." (PMID 32982786, 2020). "Dietary anti-oxidants and clinically widely used compounds, such us statins, have shown favorable pleiotropic effects partly mediated by HO-1 induction or SirT1 expression, providing a strong rationale for their therapeutic benefits in cardiovascular diseases, including AA." (PMID 32982786, 2020). "Indeed, overexpression of SIRT1 and subsequent activation of PGC-1α have been associated with a range of health benefits, including protection from metabolic decline and cardiovascular disease." (PMID 31907336, 2020). "Importantly, the metabolism of HA shares another aspect with SIRT1 activity, the contrasting action involved in cardiovascular diseases." (PMID 31932306, 2020). "These interactions suggest that positive feedback mechanisms between SirT1 and HO-1 might be at play in the vasculature, and they may affect HO-1-mediated cytoprotection in cardiovascular diseases." (PMID 32982786, 2020). "SIRT1-induction might be the result of a compensatory mechanism to counteract the adverse effects of oxidative stress in patients with cardiovascular disease." (PMID 31143479, 2019). "SIRT1 belongs to the sirtuin protein family and is well expressed in multiple tissues and organs including the heart, possesses a wide spectrum of biological activities, and is involved in the pathogenesis of cardiovascular diseases." (PMID 30050588, 2018). "SIRT1 is a known protector that delays cardiovascular diseases." (PMID 26885898, 2016). "SIRT1 activation improves endothelial function and suppresses vascular inflammation, two central pathophysiological processes involved in the initiation and progression of cardiovascular disease." (PMID 25243179, 2014). "Thus, the present study adds to the present intensive research on specific Sirt1 agonists for the treatment of cardiovascular diseases." (PMID 22493735, 2012). "Therefore, manipulation of SIRT1 activation may effectively attenuate senescence and prevent age-related cardiovascular diseases by interfering different downstream targets." (PMID 35111365, 2022). "It has been demonstrated that the FOXO family function as a SIRT1 deacetylates member that influences downstream autophagy-related pathways and regulates autophagy in numerous pathophysiological processes of diabetes, obesity, cardiovascular disease, tumor, aging, and other diseases." (PMID 36507335, 2022). "We may be able to better predict cardiovascular disorders in children by understanding the pathophysiology of the atherosclerotic diseases using a combination of clinical criteria, carotid evaluation, and epigenetic markers such as SIRT1/FOXO1." (PMID 36289866, 2022). "Furthermore, reduced Sirt1 expression was reported in monocytes of older patients with cardiovascular diseases, suggesting that aging directly aggravates cardiac dysfunction via disruption of Sirt1 signaling, promoting mitochondrial dysfunction, apoptosis, and inflammation as a result." (PMID 33303703, 2020).
cardiovascular diseases (continued). "SIRT1 has attracted considerable attention as a mediator of health and longevity in response to calorie restriction, and recent studies have shown that SIRT1 plays a protective role against cardiovascular disease by defending against oxidative stress and delaying cellular senescence." (PMID 32421926, 2020). "The Sirt1 activator resveratrol (RSV) has been demonstrated to enhance macrophage autophagy and suppress inflammatory responses in cardiovascular disease models." (PMID 40486507, 2025). "Sirtuin 1 (SIRT1), also known as nicotine adenine dinucleotide-dependent deacetylase, has shown a strong protective role in cardiovascular diseases." (PMID 38561456, 2024). "Several lncRNA–mRNA regulatory axes are involved in the action mechanisms of MSC-Exos in cardiovascular diseases, such as KLF3-AS1/sirtuin 1 (SIRT1), MALAT1/autophagy-related 4a (ATG4a), urothelial cancer associated 1 (UCA1)-Bcl-2, and Mir9-3hg/Pum2." (PMID 38812041, 2024). "This review focuses on the positive role of naturally occurring substances in enhancing mitochondrial function, particularly by influencing AMPK/SIRT1/PGC‐1α, which improves pathological states in different cardiovascular disease models." (PMID 39723061, 2024). "SIRT1, an NAD+-dependent nicotinamide adenine deacetylase, exerts preventive effects on various cardiovascular diseases." (PMID 38017499, 2023). "The protective role of the SIRT family, particularly SIRT1 and SIRT6, in cardiovascular disease has been extensively investigated over the past few decades." (PMID 38186648, 2023). "Resveratrol activates Sirtuin-1 (Sirt1) inhibiting RELA acetylation and promoting inhibitor protein-κBα (IkBα) degradation in the immune response and cardiovascular disease." (PMID 35166167, 2022). "In fact, overexpression of SIRT1 and subsequent activation of PGC-1α protects against metabolic decline and cardiovascular disease." (PMID 35548408, 2022). "Sirtuin1 (SIRT1) is a class III histone deacetylase of the Sirtuin family, which plays an important role in regulating metabolism and cardiovascular diseases and is a potential target for the treatment of various diseases." (PMID 35739982, 2022). "Many studies showed that SIRT1 activators degraded the expression of inflammatory factors and leukocyte adhesion in the aortas of mice and consequently improved VED in cardiovascular diseases." (PMID 35983375, 2022). "SIRT1, SIRT3, and SIRT6 have been shown to provide protective effects in various cardiovascular disease models, by decreasing inflammation, improving metabolic profiles or scavenging oxidative stress." (PMID 34712151, 2021). "Sirtuin-1/peroxisome proliferator-activated receptor gamma coactivator alpha (SIRT1/PGC-1α) signaling pathway is a major modulator of mitochondrial function and a vital contributor to aging and cardiovascular diseases." (PMID 34881079, 2021). "SIRT1, an NAD+-dependent class III histone deacetylase, is deemed to be responsible for the beneficial effects in the development and treatment of cardiovascular diseases." (PMID 35273493, 2021). "To demonstrate the specificity of miR-135a on Sirt1, we measured the levels of Sirt6, another SIRT family member which has common functions as Sirt1 in stress resistance, vascular aging and cardiovascular disease." (PMID 32335545, 2020). "Apoptosis of aortic smooth muscle cells can promote cardiovascular disease, but the role of parathyroid hormone (PTH) and sirtuin 1 in the pathophysiology of apoptosis is still unclear." (PMID 31106631, 2019). "Sirtuin 1 (SIRT1), a class III histone deacetylase, has been identified as a candidate molecule affecting the epigenetic mechanisms of cardiovascular disease (CVD)." (PMID 27841908, 2016). "Conversely, NF‐κB activation inhibits SIRT1/PGC‐1α signaling and drives aerobic glycolysis, particularly in cardiovascular diseases, where this interplay ameliorates metabolic dysfunction and oxidative stress while counteracting NF‐κB‐mediated inflammatory damage." (PMID 41268687, 2025).